BECN1 (beclin 1)
Diseases named in the same sentence as BECN1 in open-access papers (continued):
Sharing a sentence is not in itself a finding about the gene and the disease.
thyroid cancer (14 papers, 2011 to 2025). "Five hundred and sixty-seven miRNAs associated with nine autophagy proteins (ULK1, ATG16L1, MAP1LC3B, PRKAA1, ATG12, ATG 14, ATG5, mTOR and BECN1) were identified, of which sixty-two are accompanied by thyroid cancer, and only miR-125b is associated with the autophagy modulation in this pathology." (PMID 36980957, 2023). "Current studies have shown that knockdown of Beclin-1 causes thyroid cancer cells to lose their epithelial properties and acquire mesenchymal characters consistent with EMT through stabilizing ZEB1 mRNA, and there is a negative correlation between Beclin-1 and ZEB1 in thyroid cancer." (PMID 31126310, 2019). "Considering autophagy’s context-dependent role in tumor progression, restoring miR-30d to suppress Beclin 1-mediated autophagy is a promising approach to enhance chemotherapy effectiveness and overcome resistance in thyroid cancer." (PMID 40843353, 2025). "miRNAs have been identified as post-transcriptional regulators of Beclin 1, among which miR-30d has gained attention for its role in modulating autophagy and drug resistance in thyroid cancer." (PMID 40843353, 2025). "In thyroid cancer, studies have shown that Beclin 1 expression is upregulated in response to cisplatin treatment, contributing to autophagy-dependent drug resistance." (PMID 40843353, 2025). "Beclin 1 is a central regulator of autophagy and plays a crucial role in modulating drug resistance in various cancers, including thyroid cancer." (PMID 40843353, 2025). "For example, one study found that the expression of Beclin-1 was decreased in breast and thyroid cancer cells undergoing EMT, and that the overexpression of Beclin-1 inhibited the EMT process." (PMID 38398197, 2024). "The current study demonstrated that downregulation of Beclin 1 enhanced migration and invasion of thyroid cancer cells." (PMID 27683118, 2016). "ZEB1 activation was responsible for EMT triggered by Beclin knockdown, as knockdown of ZEB1 restored epithelial phenotype in thyroid cancer cells with Beclin 1 knockdown." (PMID 27683118, 2016). "In order to clarify the role of Beclin 1 in thyroid cancer, Beclin 1 was knockdown in thyroid cancer cell lines." (PMID 27683118, 2016). "Little previous work has been undertaken with regard to Beclin-1, thyroid cancer, and MTC specifically." (PMID 25487826, 2015). "The Beclin 1/miR-30d regulatory axis plays a pivotal role in modulating the balance between cytoprotective autophagy and apoptosis, thereby critically influencing chemoresistance in thyroid cancer." (PMID 40843353, 2025). "Metastasis of thyroid cancer is directly related to poor prognosis, thus Beclin 1 might offer potential attractive target for clinical therapy of thyroid cancer." (PMID 27683118, 2016). "Recently, it has reported that Beclin 1 also plays tumor suppressive roles in thyroid cancer." (PMID 27683118, 2016). "It has been reported that Beclin 1 exerts autophagy-independent roles in thyroid cancer cells." (PMID 27683118, 2016). "Collectively, the current study for the first time reported that Beclin 1 knockdown caused EMT and promoted invasion of thyroid cancer cells, at least partly via stabilization of ZEB1 mRNA via upregulation of AUF1 at both transcriptional and post-transcriptional levels." (PMID 27683118, 2016). "Immunohistochemistry demonstrated that most specimens demonstrated negative correlation of Beclin 1 and ZEB1 or AUF, while positive correlation of AUF1 and ZEB1 signals, further supporting increase in ZEB1 by Beclin 1 downregulation via AUF1 upregulation in thyroid cancer tissues." (PMID 27683118, 2016). "In this report we found that knockdown of Beclin 1 in thyroid cancer cells resulted in the downregulation of the epithelial marker E-cadherin and upregulation of the mesenchymal markers N-cadherin and fibronectin, with concomitant morphological changes resembling EMT." (PMID 27683118, 2016).
thyroid cancer (continued). "On the basis of existing literature, together with our current findings, the current study suggested that upregulation of AUF1 and ZEB1 by Beclin 1 knockdown seemed to be the mechanism by which haploinsufficiency of Beclin 1 gene might promote aggression of thyroid cancer cells." (PMID 27683118, 2016). "SRC, on the other hand, was significantly upregulated in BRCA, squamous cell lung cancer (LUSC) and thyroid cancer (THCA), whereas BECN1 was significantly downregulated in KIRC." (PMID 39859167, 2025). "We also found a negative correlation of Beclin 1 with AUF1 or ZEB1 in thyroid cancer tissues." (PMID 27683118, 2016).
multiple myeloma (13 papers, 2014 to 2025). "For example, J Xia demonstrated that NEK2 induces autophagy-mediated bortezomib resistance by stabilizing Beclin-1 in multiple myeloma." (PMID 33971811, 2021). "Summarizing this research, it can be concluded that higher immunoreactivity towards autophagy markers (Beclin-1 and LC3) in multiple myeloma is associated with better overall survival of MM patients." (PMID 33808304, 2021). "In multiple myeloma cell lines, pharmacologic or genetic inhibition by knockdown of Beclin-1 or Atg5, augments doxorubicin-induced cell death." (PMID 24970805, 2014). "Furthermore, pharmacologic or genetic inhibition of autophagy by knockdown of Beclin-1 or Atg5 expression augments doxorubicin-induced cell death in multiple myeloma cell lines." (PMID 28208617, 2017). "Notably, there is evidence that BCLAF1 could serve as a strong autophagy inducer by displacing beclin-1 from BCL2 in myeloma cells." (PMID 36418457, 2022).
Cognitive impairment (12 papers, 2010 to 2026). Abnormal cognition is characterized by deficits in thinking, reasoning, or remembering. "In harmony with these reports, the current findings showed that cadmium-triggered cognitive impairment was associated with hippocampal Beclin 1 decline and SQSTM-1/p62 accumulation, confirming impaired autophagy." (PMID 37630980, 2023). "BECN1 can increase autophagy rate, thus decreasing Aβ deposition, preventing cognitive impairment and finally restoring survival rate in mice models for AD." (PMID 37155564, 2023). "While it is still largely unknown how dysfunction of the autophagy pathway might contribute to neurodegeneration and AD, recent papers suggest a role for Beclin 1 (BECN1) in AD and mild cognitive impairment." (PMID 20559548, 2010). "Our findings suggest that IF intervention significantly attenuated HFD-induced cognitive impairment and neuroinflammation, increased BDNF levels, improved histological alterations, decreased Beclin-1 and p62 immunohistochemical expression, and upregulated LC3 and ATG5 mRNA expression." (PMID 42185381, 2026). "EA stimulation of Shangxing (GV23) and Fengfu (GV16) can improve cognitive impairment in rats by suppressing oxidative stress and neuroinflammation; Another study found that EA downregulated LC3 II/LC3 I and autophagosomes, and upregulated the expression of p62, mTOR and Beclin-1 in MCAO rats." (PMID 39944540, 2025). "Furthermore, AD patients with mild cognitive impairment and mild/moderate AD had higher transcriptional levels of several genes related to mitophagy, such as p62, PARKIN, dynamin 1-like, and beclin 1, compared to people without cognitive impairment." (PMID 35655270, 2022). "Future studies should address whether decreased levels of beclin 1 impair LTP in both wild type and AD mouse models, as well as the potential therapeutic benefit of increased TGF-β signaling in protecting against Aβ-induced cognitive impairments." (PMID 26692002, 2015). "Another trial have reported that G-Rg1 could improve the survival rate and ameliorated cognitive impairments partially through regulating cerebral inflammation and apoptosis which might possibly via suppressing the non-canonical beclin 1-independent autophagy pathway." (PMID 33628094, 2021).
depression (12 papers, 2014 to 2025). "The first observations indicating that autophagy could be implicated in depression were the upregulation of autophagy markers (e.g., beclin 1 and LC3II) and activation of the autophagy signaling pathway upon treatment with antidepressants." (PMID 37122628, 2023). "ULK1 was a promising therapeutic target within the autophagy framework, ULK1/Beclin‐1 initiation complex act as targeted autophagy modulation as a revolutionary pathway for developing more effective and personalised interventions for depressive disorders." (PMID 41311024, 2025). "For example, the expression of autophagy-related proteins LC3-II and Beclin-1 was significantly reduced in brain tissue in a mouse model of LPS-induced depression." (PMID 40497971, 2025). "In patients with depression, high circulating levels of beclin 1, phosphorylated Akt, and LC3II/LC3I predicted improved clinical antidepressant effect suggesting that antidepressants stimulate macroautophagy induction and autophagosome formation." (PMID 37122628, 2023). "Several studies have reported that antidepressants can increase the expression of autophagy marker, beclin-1, in neural cells and animal models of depression." (PMID 31244689, 2019). "Depression scores and serum levels of beclin-1 were measured at the baseline and after 8 weeks of antidepressant treatment." (PMID 31244689, 2019). "These contradictory findings indicate that the role of beclin-1 in major depression and action of antidepressants are rather complex." (PMID 31244689, 2019). "In addition, importantly, a significant positive correlation was observed between baseline expression levels of beclin-1 in peripheral blood mononuclear cells (PBMCs) and clinical response after 6 weeks of antidepressant treatment in patients with depression." (PMID 31244689, 2019). "Additionally, increasing the sample size could provide more robust evidence to evaluate whether BECN1 can serve as a potential target for depression treatment." (PMID 39940841, 2025). "Further clinical studies have shown that changes in the levels of the autophagy marker Beclin-1 are strongly associated with the response to medication for depression and that Beclin-1 may serve as an independent predictor of the efficacy of medication for depression." (PMID 40497971, 2025). "Similar results were also seen in the CSDS-induced mouse model of depression, where the expression of autophagy-related proteins such as LC3-II/I, Beclin-1, ATG5, and ATG7 was significantly decreased in the hippocampus after 10 days of stress exposure." (PMID 40497971, 2025). "Upregulation of beclin 1 and LC3 have been observed in depression-like behavior induced by electroconvulsive shot and downregulation occurs in pain-, bacterial endotoxin lipopolysaccharide-, and maternal separation-induced depression-like behavior." (PMID 37122628, 2023). "To firstly provide the direct evidence linking the interaction between autophagy and neuroimmune system to depression, we assessed the expression of autophagic biomarkers, including LC3-II/I and Beclin-1, in the hippocampus of rats following sustained immune stimuli." (PMID 29212498, 2017).
diabetic cardiomyopathy (11 papers, 2013 to 2023). Diabetic cardiomyopathy is a disorder of the heart muscle in people with diabetes. "In exploring the molecular mechanisms, it was found that miR-30c suppressed autophagy in diabetic cardiomyopathy via targeting BECN1, through direct binding to BECN1 3′ UTR." (PMID 30103495, 2018). "In conclusion, SCU may alleviate diabetic cardiomyopathy by upregulating the autophagy-related factors (Beclin-1, LC3-I, and LC3-II) and downregulating apoptosis-related factors (caspase-3, caspase-8, caspase-9, caspase-12, Bax, and Cyt-C) of cardiomyocytes." (PMID 35571612, 2022). "Indeed, our results suggest that overexpression of HO-1 enhances the phosphorylation of AMPK and increases LC3-II and Beclin-1 expression in diabetic cardiomyopathy." (PMID 24086665, 2013). "In our study, the expression of LC3II and P62 was increased, whereas the expression of beclin 1, LAMP2, and cathepsin D was inhibited in the myocardium during diabetic cardiomyopathy and in PA-induced NMCMs." (PMID 37658156, 2023). "Taken together, our results demonstrated that continued administration of 9-PAHSA alleviated diabetic cardiomyopathy in db/db mice.9-PAHSA treatment increased cardiac autophagy possibly via up-regulation of PI3KIII and BECN1 and down-regulation of mTOR and p-Akt in diabetic myocardium." (PMID 34867366, 2021).
endometrial cancer (11 papers, 2014 to 2025). Primary or metastatic malignant neoplasm involving the endometrium (mucous membrane that lines the endometrial cavity). "LncRNA FIRRE facilitates autophagy and attenuates the radiosensitivity of endometrial cancer by orchestrating the miR-199b-5p/SIRT1/BECN1 axis." (PMID 39281375, 2024). "Lower levels of FOXO1 and Beclin-1 correlate with worse pathological types of endometria, worse prognoses, and a higher likelihood of developing endometrial cancer." (PMID 37962467, 2024). "In endometrial cancer, metformin decreases cell viability and proliferation in a human endometrial cancer cell line (Ishikawa cells) through activation of pAMPK, induction of beclin 1, down-regulation of IGF, and increased autophagy and apoptosis." (PMID 39588311, 2024). "In addition, HOTAIR can regulate the cisplatin-sensitivity of endometrial cancer via the regulation of autophagy by affecting Beclin-1 expression." (PMID 37171645, 2023). "However, in conditions of autophagy, the silencing of Beclin 1 using siRNAs and chloroquine sensitized endometrial cancer cells to sorafenib treatment." (PMID 31850214, 2019). "In a previous study, both Beclin 1 and LC3 were shown to increase when HEC-1A endometrial cancer cells were treated with chrysin." (PMID 35884773, 2022). "Interestingly, an increased expression of Beclin-1, ATG5, ATG7 and LC3 has been related to the development of metastatic endometrial carcinoma to the lymph nodes." (PMID 39596186, 2024). "Studies have shown that the autophagy markers Beclin-1 and LC3 are significantly increased in patients with non-PCOS endometrial cancer, and that elevations in their levels correlate positively with tumor grade and myometrial invasion, and negatively with 5-year survival rate." (PMID 37962467, 2024).
Insulin resistance (11 papers, 2012 to 2024). Increased resistance towards insulin, that is, diminished effectiveness of insulin in reducing blood glucose levels. "It has been reported that hyperactive BECN1 can activate autophagy in response to cellular stress caused by insulin resistance, helping to alleviate the pathology, enhance systemic insulin sensitivity, and regulate energy metabolism." (PMID 39610878, 2024). "BECN1, a protein essential for autophagy, is involved in adipocyte differentiation, lipolysis and insulin resistance." (PMID 34085745, 2021). "BECN1 is involved in adipocyte differentiation, lipolysis and insulin resistance." (PMID 34085745, 2021). "Similarly, the upregulation of BECN1 acts as a defense mechanism in insulin resistance." (PMID 39610878, 2024).
preeclampsia (11 papers, 2017 to 2025). Preeclampsia is a hypertensive disorder of pregnancy that is characterized by new-onset hypertension with proteinuria presenting after 20 weeks of gestation, and depending on mild or severe forms may initially present with severe headache, visual disturbances, and hyperreflexia. "Secondly, while focused on PDE3A as a key downstream effector of IGF2BP3, we acknowledge the emerging significance of apoptotic and autophagic regulators such as BCL-2 and Beclin-1 in preeclampsia and HELLP syndrome." (PMID 40563987, 2025). "Higher predicted expression of 12 genes (including ATG16L1, BECN1, EP300, SGK1) was associated with increased odds of preeclampsia, while higher predicted expression of 17 genes was associated with decreased risk." (PMID 41220585, 2025). "This was followed by a study in the human placenta, which showed a lower level of LC3B/Beclin-1 ratio in early-onset preeclampsia compared to normal pregnancy, late-onset preeclampsia, and even IUGR." (PMID 34805141, 2021). "On the other hand, autophagy occurs as a result of hypoxia or starvation in preeclampsia where death receptors in the plasma membrane are triggered, leading to activation of Beclin-1, thus enhancing autophagy rate." (PMID 34805141, 2021). "There was a significant difference between these groups in the MAP1LC3B/BECN1 ratio as marker of the trophoblast survival capacity with a significantly reduced ratio in villous trophoblast of early-onset preeclampsia." (PMID 30408071, 2018). "He confirmed that LC3 and Beclin-1 expression in the syncytiotrophoblast and vessel endothelial cells of placentas of patients with early-onset preeclampsia (<34 gestational weeks)." (PMID 29991702, 2018). "Early-onset preeclampsia and IUGR had the highest autophagy protein expression levels, while normal pregnancy and late-onset preeclampsia had the highest LC3B/Beclin-1 ratio." (PMID 29107968, 2017). "The correlation for early-onset preeclampsia shows that the lower the ratio of LC3B/Beclin-1 (i.e. the worse cell survival is preserved) the higher the free LDH levels." (PMID 29107968, 2017). "On the other hand, LC3-II overexpression was only observed in the placenta of preeclamptic women when associated with fetal growth restriction, and significantly increased expression of LC3 and beclin-1 was detected in placentas from pregnancies complicated by early-onset preeclampsia." (PMID 36629523, 2022). "Moreover, the expression of LC3 and Beclin-1 was highly increased in early-onset preeclampsia group compared to normal controls." (PMID 29991702, 2018). "A recent study has suggested that the oxidative stress environment in preeclampsia causes an increase in de novo synthesis of ceramides, resulting in increased autophagy in trophoblast, by activating the MAPK8/JNK1 pathway which frees Beclin-1 to initiate autophagy." (PMID 34805141, 2021). "Serum and placental samples from four groups of cases; normal term, IUGR, early-onset and late-onset preeclampsia, were analyzed for 25(OH)D vitamin D, sFLT1, PGF, LGALS13 in serum and vitamin D receptor (VDR), MAP1LC3B and BECN1 in placental tissues." (PMID 30408071, 2018). "Early-onset preeclampsia and IUGR had median levels of Beclin-1 expression higher than the median population." (PMID 29107968, 2017). "In the early-onset preeclampsia and IUGR groups, mean Beclin-1 staining was higer than the median population." (PMID 29107968, 2017). "Early-onset preeclampsia and IUGR had the highest expression, while normal pregnancy and late-onset pregnancy had highest LC3B/Beclin-1 ratios." (PMID 29107968, 2017). "Furthermore, there was a strong and significant correlation between the MAP1LC3B/BECN1 ratio as survival marker and VDR levels in the early-onset preeclampsia group." (PMID 30408071, 2018).
preeclampsia (continued). "It has been reported that the expression of BECN1, involved in autophagosome formation in mammalian placentas, is higher in the presence of FGR without preeclampsia, but not when preeclampsia is present." (PMID 31083536, 2019).